CXCR3 (C-X-C motif chemokine receptor 3)
Diseases named in the same sentence as CXCR3 in open-access papers (continued):
Sharing a sentence is not in itself a finding about the gene and the disease.
vitiligo (continued). "For example, CXCL9 and CXCL10 induced by IFN-γ play a key role in the skin migration of CD8+ T cells in vitiligo, and the expression of CXCR3 on melanocyte-specific CD8+ T cells has been detected in skin lesions and in the peripheral blood of vitiligo patients." (PMID 33679890, 2021). "The recruitment of CD8+ T cells to skin lesions is carried out by the IFN-γ-mediated T cell chemokine receptor, C-X-C motif chemokine receptor 3 (CXCR3), and its ligands CXCL9, CXCL10, and CXCL11, which are found to be abundant in skin biopsy specimens from vitiligo patients." (PMID 33613564, 2020). "The chemokine receptor CXCR3 (the receptor for the chemokines CXCL9 and CXCL10) was shown to be important for epidermal localization of effector T cells and TRM cell development, which led to studies on CXCR3 expression in vitiligo patients." (PMID 31230406, 2019). "Furthermore, serum CXCL10 levels were associated with Vitiligo Area Scoring Index (VASI) of patients with progressive vitiligo, suggesting that the CXCL10/CXCR3 axis mediates T-cell recruitment into the skin of progressive vitiligo." (PMID 31649667, 2019). "For instance, transfusion of CXCR3−/− PMEL T cells in vitiligo prone mice did not evolve to phenotypic alterations." (PMID 31849996, 2019). "The recruitment of CD8+ T-cells to skin lesions is carried out by the IFN-γ-mediated T-cell chemokine receptor, C-X-C motif chemokine receptor 3 (CXCR3), and its ligands CXCL9, CXCL10, and CXCL11, which are abundant in skin biopsy specimens from patients with vitiligo." (PMID 29928282, 2018). "In the context of Th17 inhibition, the Th1 immune response may be relatively active due to lack of regulation, thereby enhancing the activation of the IFN-γ/CXCL10 axis, promoting CXCR3+ CD8+ T cell recruitment and melanocyte destruction, and inducing or aggravating vitiligo." (PMID 40861456, 2025).
colorectal cancer (42 papers, 2009 to 2026). A primary or metastatic malignant neoplasm that affects the colon or rectum. "CXCL9 (chemokine ligand 9) mediates the recruitment of tumor-suppressive CXCR3+ T cells and NK cells and is significantly associated with improved prognoses for breast and colorectal cancers." (PMID 32513298, 2020). "Therefor in this review, we discuss the divergent roles of CXCR3 and its ligands on the induction of peripheral inflammation vs suppression of tumor number and size via different mechanisms in colorectal cancer associated with intestinal inflammation." (PMID 29707158, 2018). "High CXCR3 expression is associated with poor survival in glioblastoma and colorectal cancer." (PMID 31696204, 2019). "CXCR3 has been strongly associated with tumor progression in advanced colorectal cancer." (PMID 29707158, 2018). "In colorectal cancer, CXCR3 expression correlates with lymph node metastasis and poor prognosis, where CXCL10 enhances cell survival and invasion partly via matrix metalloproteinase-9 (MMP-9) upregulation." (PMID 41516196, 2025). "Prompted by this observation, we derived the NK_CXCR3 signature from the top 25 expressed genes and assessed its prognostic value in colorectal cancer liver metastases using a publicly available microarray dataset." (PMID 40168086, 2025). "For example, TGF-β produced by CAFs or M2 macrophages in the TME was found to inhibit the expression of CXCR3 on the surface of cytotoxic T cells in a murine model of colorectal cancer." (PMID 39596815, 2024). "CXCL9/10/11 can recruit immune cells, including CD8+ T cells, Th1 cells, and NK cells, to reach tumor sites, thereby inhibiting the progression of colorectal cancer through the binding of CXCR3 protein to immune cell surface sites." (PMID 38275602, 2024). "TNF-α promotes epithelial-–mesenchymal transition by stimulating the CXCL10/CXCR3 axis of colorectal cancer cells." (PMID 37048082, 2023). "In conclusion, numerous studies have shown that CXCR3 promotes metastasis of colorectal cancer to lymph nodes." (PMID 36479091, 2022). "Similar to colorectal cancer expression, it has been indicated that CXCR3 and its ligand axis can promote cancer cell proliferation and metastasis in esophageal cancer." (PMID 36479091, 2022). "CXCR3 is detected in approximately one-third of early colorectal cancer tumor specimens, and patients with CXCR3-positive tumors tend to have lymph node metastases more often, suggesting that CXCR3 is an independent risk factor for poor prognosis." (PMID 36479091, 2022). "Fulton verified in an experimental model of colorectal cancer animal metastasis that inhibition of CXCR3 expression in tumor-bearing mice reduced the probability of lung metastasis of tumors." (PMID 36479091, 2022). "For example, in clinical colorectal cancer patients, CXCR3 expression levels are significantly higher in lymph nodes (LN) and metastases in the liver compared with those in primary tumors." (PMID 36479091, 2022). "Sato E had verified CXCL10 was an inhibitor to growth and metastases in tumor, and different expression level in CRC patients had different prognostic In Jessicca D. Abron’s study, he investigated the role of CXCR3 in inflammation and colorectal cancer." (PMID 30973890, 2019). "It has been demonstrated an important role of chemokine receptor 3 (CXCR3) and its ligands in both inflammation and colorectal cancer." (PMID 31031748, 2019). "The literature unequivocally shows the importance of CXCR3 expression on Tregs, Teffs, and macrophages in colorectal cancer induction and progression." (PMID 29707158, 2018). "CXCR3 expression on Tregs and Teffs in tumors represents an under investigated area and functional characterization of CXCR3 induction on Tregs and Teffs function in colorectal cancer needs further in-depth study." (PMID 29707158, 2018).
colorectal cancer (continued). "MC38-luc colorectal cancer grew faster in CXCR3−/− mice than the wild type mice, as shown by parameters in both optical light imaging and real tumor burden (weight)." (PMID 26956047, 2016). "CXCL10 secreted from CXCR3-expressing colorectal carcinoma cells promotes, by an autocrine mechanism, some progression-promoting functions in these tumor cells." (PMID 22408433, 2012). "The infiltrating Th1 cells secrete IFNγ, which, in addition to its immune functions, promotes the release of CXCL10 from IFNγ receptor-expressing colorectal carcinoma cells while up-regulating CXCR3 expression." (PMID 22408433, 2012). "Thus, in addition to CD8, CXCR3 has potential as a prognostic marker for the TiME, and further validation studies for CXCR3 are needed in colorectal cancer." (PMID 39409972, 2024). "CXCL9, CXCL10, CXCL11/CXCR3 axis has been proved to regulate immune cell migration, differentiation, and activation, leading to tumor suppression in pancreatic adenocarcinoma, colorectal cancer and so on." (PMID 34777466, 2021). "Enhancing the accumulation of IFN-Υ producing CD8+ Trm in the large intestine in a CXCR3-dependent manner might have important implications for cancer immunotherapy, particularly in the case of colorectal cancer (CRC)." (PMID 32901029, 2020). "The presence of high CXCR3 expression on CD8 T cells in colorectal cancer has been reported." (PMID 31696204, 2019). "CXCR3 is functionally expressed on Tregs in colorectal cancer." (PMID 31696204, 2019). "Similarly, high expression of CXCL11 in a colorectal cancer model was shown to recruit CXCR3+ Tregs." (PMID 30319622, 2018). "In contrast, TS induced CXCR3 expression of CD4+Tregs at peripheral sites suppress the immune response and systemic inflammatory cytokines, thus reducing inflammation and leading to effective suppression of both colitis and associated colorectal cancer." (PMID 29707158, 2018). "18%–34% of colorectal cancer (CRC) patient samples show strong CXCR3 staining, and most of these CXCR3-positive patients are also diagnosed with lymph node metastasis." (PMID 40786052, 2025). "However, CXCR3 and its ligands have been shown to increase during colitis, but the role that these chemokines play in pathogenesis, disease susceptibility and progression of colorectal cancer is not very clear." (PMID 29707158, 2018). "In contrast TS also induces CXCR3 and its ligand level and expression in the TME of DSS-AOM induced colorectal cancer as compared to normal mice." (PMID 29707158, 2018). "Further, in a similar study, we noticed that CXCR3 and its ligands are important during Teff entry into colon tumors in the Azoxymethane (AOM) and dextran sodium sulphate (DSS)- induced models of colorectal cancer." (PMID 29707158, 2018). "In this review, we discussed the differential role of CXCR3 during peripheral inflammation and TME in colorectal cancer." (PMID 29707158, 2018). "This is consistent with the recent finding that CXCR3 and another ligand CXCL10 promote invasion-related properties in colorectal cancer." (PMID 22438977, 2012). "The probability of metastasis to the lung or liver in colorectal cancer is not affected by altered CXCR3 expression levels." (PMID 36479091, 2022). "We demonstrated that CXCR3 decreased in the CD8+ T cells of patients with lung cancer compared to those of healthy volunteers, which has also been reported previously in patients with colorectal cancer." (PMID 34680466, 2021).
Autoimmunity (38 papers, 2014 to 2026). The occurrence of an immune reaction against the organism's own cells or tissues. "CXCR3 signaling has been implicated in myriad inflammatory diseases, including autoimmunity, inflammatory bowel disease (IBD), transplant rejection, infection, and cancer." (PMID 28667746, 2017). "Although infection-induced arthritis could be different from autoimmunity-associated arthritis, the effectiveness of CxCR3 antagonist in reducing collagen induced inflammatory arthritis in mice supports our data." (PMID 35924250, 2022). "More research is needed to fully comprehend the role of decreased CXCR3 expression in SIGMD patients for the development of autoimmune conditions, including AILD." (PMID 39128050, 2024). "Among the large chemokine and chemokine receptor families, CXCR3 and CXCR3‐binding chemokines are likely to be key players in the maintenance and amplification of the autoimmunity‐related inflammatory processes." (PMID 37647423, 2023). "Our data suggest that a subset of innate B-1 cells, identified by classical markers (Bhlhe41, Cd43, and IgM) and context-specific markers (Cxcr3 and Itgb1), can contribute to autoimmunity in BOS, and thus represent potential therapeutic value." (PMID 36134664, 2022). "The abundance of Desulfovibrio piger is associated with a higher level of plasma 1-arachidonoyl-GPC, a metabolite known to negatively affect CD4+, CXCR3+, CD8+, and CXCR3+ T cells, preventing further progression of autoimmunity." (PMID 36341463, 2022). "Here, we provide in vivo evidence using genetic approaches demonstrating that DRD3 in B cells mediates the upregulation of CXCR3 and α4-integrin, thus affecting the recruitment of important B-cell subsets into the CNS upon the development of CNS autoimmunity." (PMID 34920747, 2021). "In this regard, both α4-integrin (CD49d) and the chemokine receptor CXCR3 have been involved in the infiltration of B cells into the CNS upon autoimmunity." (PMID 34920747, 2021). "In line with previous literature, we propose that D. piger dampens autoimmunity in T1D via plasma 1-arachidonoyl-GPC thus affecting CXCR3+ T cells." (PMID 33106354, 2021). "We also analyzed Th1/17 (CCR6+CXCR3+) cells which were originally related to autoimmunity, but recently turned out to be significant in microorganism infections including dengue virus." (PMID 33072068, 2020). "Further, Th17 cells expressing CXCR3+CCR6+ are associated with protection against Mtb, while those displaying CCR6+ CCR4+ are involved in autoimmunity." (PMID 28985739, 2017). "A role of CXCR3 in T cells and T-cell-mediated autoimmunity has been well established; however, its role in B cell trafficking and antibody-mediated autoimmunity is beginning to emerge." (PMID 28928736, 2017). "A role of decreased expression of CXCR3 on B cell subsets in SIGMD and autoimmunity associated with SIGMD remains to be investigated." (PMID 28928736, 2017). "Our data provides a set of genes with epigenetic alteration likely to be indicators of autoimmunity and emphasizes the role of CXCR3 in the natural history of PBC." (PMID 26150899, 2015). "In activated T cells, CXCR3 expression is also important for the amplification of IFNγ-mediated recruitment into peripheral sites during infection and in autoimmunity." (PMID 24586509, 2014). "CXCR3 (GPR9/CD183) has also been studied as target for autoimmunity and cancer." (PMID 36275816, 2022). "While we have not addressed whether anti-insulin B cells are specifically recruited via a chemokine receptor, it is conceivable that anti-insulin B cells express high levels of C-X-C motif chemokine receptor 3 (CXCR3), a chemokine receptor involved in recruitment of lymphocytes in autoimmunity." (PMID 31444529, 2019).
Autoimmunity (continued). "Taking this into consideration, our results may suggest that reducing the availability of glutamine to the CD4+ cells might have beneficial effect on reducing T cells promoting autoimmunity by decreasing pathogenic CCR6 and CXCR3 bearing T cell and increasing regulatory T cells." (PMID 27467144, 2016). "Recent literature suggests that certain pathogenic Th17 cell subsets with Th1 characteristics, such as CD4+CD161+CCR6+CXCR3+IL-17+IFN-y+ (Th17.1) and CD4+CD161+CCR6+CXCR3+IL-17-IFN-y+ (exTh17), are important contributors in Th1-mediated autoimmunity." (PMID 35967358, 2022). "However, in both T1D and SD-like manifestations in NOD mice, autoimmunity develops spontaneously suggesting that while CXCR3+ regulatory T cells may limit immunopathology in affected organs, they are incapable of preventing disease development in the first place." (PMID 33916486, 2021). "In conclusion, we have identified novel anti-GPCR abs against the chemokine receptors CXCR3 and CXCR4 in patients with systemic sclerosis linking autoimmunity with interstitial lung disease." (PMID 29566745, 2018). "CXCR3 is involved in the direction of CD4+ and CD8+ T-cells in context of cancer and autoimmunity." (PMID 36157879, 2022). "Specifically, while the proportion of pancreatic regulatory T cells was relatively unchanged in the absence of these CXCR3+ regulatory T cells, their absence resulted in accelerated progression of T1D demonstrating their importance in modulating autoimmunity." (PMID 33916486, 2021). "Up to date, the best characterized Th-like Treg subset in autoimmunity is the Th1-like Treg cells, with upregulated expression of transcription factor Tbet, chemokines CCR5 and CXCR3, stable Foxp3 expression due to highly demethylated TSDR region and increased production of IFN-γ cytokine." (PMID 34539668, 2021). "CXCR3 binds and traffics toward its IFNγ-inducible ligands, CXCL9, 10, and 11, which are expressed primarily in activated CD8+ T cells, NK cells, and CD4+ TH1 cells and play critical roles in recruiting and retaining T cells during infection, autoimmunity and cancer." (PMID 39409972, 2024). "Since CXCL11-mediated stimulation of CXCR3 has been consistently involved in the lymphocyte infiltration into the CNS in mice and humans upon CNS autoimmunity, we next addressed whether propionate-mediated GPR43 stimulation was able to affect the CXCL11-CXCR3 migration of IEL TCRαβ+ T-cells." (PMID 37264394, 2023). "We propose that the anti-CXCR3 antibody treatment alleviates inflammatory cell infiltration and further reduces inflammatory cytokine production after CVA2 infection, which finally prevents the subsequent destruction of the organs or tissues from uncontrollable cell-mediated autoimmunity." (PMID 35604176, 2022). "CXCR3− CCR6+ cTfh cells in IRs may suggest their role in autoimmunity, rather than CD4+ recovery." (PMID 40130906, 2025).
lupus (37 papers, 2010 to 2025). "Loss of CXCR3 in the MRL/lpr lupus strain results in significantly reduced renal T cell infiltration and improved disease." (PMID 37790939, 2023). "A recent report demonstrated that CXCR3 deficiency decreases autoantibody production and inhibits aberrant activated T follicular helper cells and B cells in lupus mice." (PMID 37790939, 2023). "A possible role for IP-10 in the development of LN was also supported by the amelioration of nephritis in lupus-prone MRL/lpr mice with IP-10 receptor (CXCR3) deficiency." (PMID 35683585, 2022). "While both CXCR3 and its ligands are increased in the kidney of lupus-prone mice with LN, their deficiencies in lupus-prone mice have shown inconsistent or even contradictory results." (PMID 27403037, 2016). "In conclusion, the prevalence or concomitant existence of these mechanisms (local generation versus migration of CXCR3+ early-differentiated plasma cells) as well as their pathogenic relevance in lupus, clearly deserve very interesting additional investigations." (PMID 23520491, 2013). "Cutaneous lupus lesions exhibit CXCR3-mediated trafficking of memory/effector T cells via CXCL9-11, perpetuating skin damage." (PMID 40552145, 2025). "Previous reports demonstrated that CXCR3+ cells are recruited into inflamed kidneys in lupus prone mice and human lupus patients." (PMID 37790939, 2023). "Reduced Fli-1 expression in lupus mice leads to decreased renal Cxcl10 mRNA levels and renal infiltrating CXCR3+ T cells that parallels reduced renal inflammatory cell infiltration and renal damage." (PMID 37790939, 2023). "The CXCL10/CXCR3 axis plays a role in the pathogenesis of various inflammatory diseases including lupus." (PMID 37790939, 2023). "CXCR3 plays an important role in mouse and human lupus, by regulating infiltration of Th1 and Th17 cells into the kidney." (PMID 32183259, 2020). "This is evident in the murine lupus model showing an increased expression of IP-10 and its receptor CXCR3 correlating with the migration of lymphocytes into lung tissue." (PMID 31597273, 2019). "An increased number of CXCR3+ cells were also found in lupus nephritis and in atherosclerotic lesions secondary to systemic lupus erythematosus (SLE)." (PMID 29566745, 2018). "It is further notable that plasma cells expressing CXCR3 also localize into inflamed kidneys of lupus mice." (PMID 24945254, 2014). "CXCR3 is also expressed on subpopulations of memory B cells and plasma cells from lupus patients and it has been demonstrated that plasma cell precursors migrate toward gradients of CXCR3 ligands." (PMID 24945254, 2014). "CXCR3+CD4+ T cells are significantly elevated in the urine of lupus patients with active nephritis flares and are a useful biomarker for renal disease activity." (PMID 24945254, 2014). "Supporting this hypothesis, CXCR3+ PC subsets have been identified in the BM, spleen, and inflamed kidneys of other lupus-prone mice, where they contribute to autoantibody production." (PMID 41213970, 2025). "Due to the high expression of CXCR3+ T cells in lupus skin samples, it was implied that cTFH1 cells may have migrated into the skin." (PMID 36293075, 2022). "Importantly, studies have shown that CXCR3 and its ligands are increased in the nephritic kidney of lupus-prone mice, suggesting migration of CXCR3-expressing effector cells from the secondary lymphoid organs into the inflamed kidney." (PMID 27403037, 2016). "Moreover, it has been found that CXCR3+ cells are accumulated in tubulointerstitial regions and around glomeruli in the kidney of lupus nephritic patients, account for 60% of total infiltrating cells, and are positively correlated with proteinuria." (PMID 27403037, 2016). "Interestingly, autoreactive cells specific for the Sm autoantigen have been shown to be enriched in a subset of circulating CD19high plasma cell precursors expressing high levels of CXCR3, in lupus patients with poor clinical outcome." (PMID 23520491, 2013).